CNN2 (calponin 2)
Diseases named in the same sentence as CNN2 in open-access papers (continued):
Sharing a sentence is not in itself a finding about the gene and the disease.
lymphoma (1 paper, 2025). A malignant (clonal) proliferation of B- lymphocytes or T- lymphocytes which involves the lymph nodes, bone marrow and/or extranodal sites. "WES revealed significantly mutated genes, including several known (NCF1, MMP9, and VDR) and possibly other candidate (CNN2, MUC4, MTSS2, KMT2C, HAVCR2, and TCF19) genes, most of which were associated with the physiological activation of lymphoma cells." (PMID 41296384, 2025).
metastatic cancer (1 paper, 2020). A carcinoma which has spread from the original site of growth to another anatomic site. "Reduced expression of calponin 2 is found in metastatic cancer cells." (PMID 32185166, 2020).
muscular dystrophies (1 paper, 2022). "They suggested a detailed analysis of the connective tissue growth factor/cellular communication network 2 (SPG25/CNN2) at 6q23.2 has elevated CNN2 protein, thereby inducing neuromuscular pathologies such as neurodegenerative disorders, muscular dystrophies, and muscle overuse." (PMID 35163618, 2022).
pancreatic cancer (1 paper, 2017). "After the inhibitor treatment for 48 h, protein expression of PCNA was significantly down-regulated in pancreatic cancer cells, more in calponin 2 knockdown cells." (PMID 28915602, 2017). "The inhibitory effect of calponin 2 overexpression on proliferation and migration of pancreatic cancer cells was moderate." (PMID 28915602, 2017). "Inhibiting AKT and NF-κB pathways significantly reduced the proliferation of calponin 2-knockdown pancreatic cancer cells." (PMID 28915602, 2017). "Knockdown of calponin 2 facilitated pancreatic cancer cell proliferation and metastasis." (PMID 28915602, 2017). "However, the role of calponin 2 in pancreatic tumor growth, metastasis and patient survival remains unclear." (PMID 28915602, 2017).
primary biliary cholangitis (1 paper, 2020). Primary biliary cholangitis (PBC) is a chronic and slowly progressive cholestatic liver disease of autoimmune etiology characterized by injury of the intrahepatic bile ducts that may eventually lead to liver failure. "Our results suggest that hsa-miR-23b is involved in pathophysiology of primary biliary cholangitis through interleukin-12 signaling via regulation of CNN2, JAK1, LMNB1, MTAP, SOD2, and TCP1." (PMID 33036164, 2020).
sarcoidosis (1 paper, 2022). Sarcoidosis is a multisystemic disorder of unknown cause characterized by the formation of immune granulomas in involved organs. "Among the three immune-related genes with significant mutation frequencies, the PRSS3 and CNN2 genes were detected, which contained the highest missense mutation ratios, at 100% and 97%, respectively, among the 116 sarcoidosis patients." (PMID 35860586, 2022). "In our study, we identified a C>A missense mutation (rs78251590) on CNN2 that may participate in the regulation of immune regulation of sarcoidosis." (PMID 35860586, 2022). "Furthermore, non-synonymous SNPs in LILRB2, GZMB, APOL1, CNN2, SWAP70, and CSF1R were shown in over 50% of sarcoidosis patients." (PMID 35860586, 2022).
tumor (15 papers, 2011 to 2026). "E-cadherin, the loss of which contributed to an EMT process and promoted tumor metastasis, was downregulated and vimentin, fibronectin, Snail and Slug were upregulated after calponin 2 knockdown in PDAC cells." (PMID 28915602, 2017). "Further comparison of the representative images and statistical analysis suggested that the up-regulated CNN2 in CRC may be associated with tumor development and lymphatic metastasis." (PMID 37188478, 2023). "Conversely, a lot more studies revealed the role of CNN2 in human cancers as a tumor-promoting molecule." (PMID 37188478, 2023). "A tissue microarray, containing 90 CRC tumor tissues and 78 para-carcinoma normal tissues, was used for IHC analysis to show the expression pattern of CNN2 in CRC." (PMID 37188478, 2023). "Recent research indicates that CNN2 plays a role in the proliferation, differentiation, and migration of tumor cells." (PMID 37373013, 2023). "The positive rate of CNN2 mRNA in HCC was significantly higher than that in other tumor tissues (p < 0.05)." (PMID 37373013, 2023). "Research based on clinical samples showed the up-regulation of CNN2 in CRC and its association with tumor development, metastasis, and poor prognosis of patients." (PMID 37188478, 2023). "In this study, our in vitro and in vivo results also recognize CNN2 as a tumor promoter in the development and progression of CRC." (PMID 37188478, 2023). "We also analyzed the expression levels of CNN2 in tumor cell lines and tissues to explore its potential as a molecular biomarker for HCC." (PMID 37373013, 2023). "Taken together, AFAP1-AS1/LINC01419-miR-143-5p-PAK4/CNN2 represents a potential tumor-promoting up-down-up axis." (PMID 35629368, 2022). "Since the actin cytoskeleton plays a central role in cell division and motility, calponin 2 plays a role in inhibiting cell proliferation and migration, which implicates an involvement in tumor genesis and progression." (PMID 28915602, 2017). "In this test, calponin 2 expression and tumor differentiation state remain significantly different between groups (P < 0.05 and P < 0.01, respectively)." (PMID 28915602, 2017). "Taking together, the clinical data and cellular experiments reported in the present study strongly support the notion that calponin 2 is an inhibitory modulator of tumor progression, and therefore a possible new molecular target for cancer therapy." (PMID 28915602, 2017). "Calponin 2 was highly expressed in 60 of the 119 tumor tissues (50.42%) and in 13 of the 99 non-tumor tissues (13.13%)." (PMID 28915602, 2017). "Overexpression of calponin 2 inhibited PDAC tumor cells proliferation and migration, whereas reduction of calponin 2 in PDAC cells resulted in increased proliferation and migration rate." (PMID 28915602, 2017). "To further confirm the inhibitory function of calponin 2 in PDAC tumor cell proliferation and migration, we inhibited calponin 2 expression with RNA interference (RNAi) in the PDAC cell line MIA-PaCa2." (PMID 28915602, 2017). "Patients with high calponin 2 expression in tumor cells had more favorable survival rate than those with low expression." (PMID 28915602, 2017). "In the present study, we compared the expression of calponin 2 in PDAC tissues and non-tumor tissues from 119 patients and analyzed the correlation between the level of calponin 2 expression and clinicopathological parameters and survival." (PMID 28915602, 2017). "Therefore, investigating the expression level of CNN2 in tumor tissues and its correlation with tumor development will offer a new theoretical foundation for targeted therapy of HCC." (PMID 37373013, 2023). "The expression of CNN2 in tumor tissues was significantly higher than in normal tissues." (PMID 37188478, 2023). "In conclusion, CNN2 was discovered as a tumor promoter in CRC, which was up-regulated in CRC and could promote CRC development through regulating cell phenotypes." (PMID 37188478, 2023).
tumor (continued). "If the tumor is malignant CNN2 is employed to characterize it as LGG or HGG." (PMID 30669406, 2019). "Our working hypothesis is that the expression level of calponin 2 in tumor cells has an inverted correlation with malignancy in terms of metastasis and prognosis." (PMID 28915602, 2017). "However, the expression level and cellular distribution of CNN2 remain unclear, and the impact of its increased or decreased expression on tumor cells has yet to be studied." (PMID 37373013, 2023). "In addition to muscle cells, CNN2 also shows some regulatory role in tumor cell phenotypes." (PMID 37188478, 2023). "The mechanism underlying CNN2’s involvement in tumor metastasis is not yet fully understood." (PMID 37373013, 2023). "Whether CNN1 is an oncogene like CNN2 or a tumor suppressor gene in breast remains unknown." (PMID 31986487, 2020). "Therefore, the expression of calponin 2 in PDAC tumor cells may reflect epithelial-mesenchymal transition." (PMID 28915602, 2017). "Increased MIF, CNN2, and ARF1 are enriched in IL-12-related pathways, which promote tumor development." (PMID 38072118, 2023). "In this study, EGR1 was screened as a potential downstream of CNN2, which possessed a similar expression pattern in CRC (higher in tumor tissues than in normal tissues)." (PMID 37188478, 2023). "C, TCGA prostate co-expression matrix for CNN2/TAGLN2 PGG family genes and pseudogenes across tumor samples." (PMID 31029062, 2019). "Calponin 2 is correlated to less tumor metastasis in patients with PDAC, and increased calponin 2 expression predicted a better prognosis." (PMID 28915602, 2017). "To determine the role of calponin 2 in PDAC, we first examined the expression of calponin 2 in PDAC and adjacent non-tumor tissues using immunohistochemistry." (PMID 28915602, 2017). "CNN2 is also known to activate PKC phosphorylation, a key mechanism that mediates growth arrest in tumor cell lines." (PMID 25136288, 2014). "The diminishment of CNN2 expression in CRC cells could significantly block cell proliferation in vitro and tumor growth in vivo." (PMID 37188478, 2023). "Additionally, CNN2 is a potential molecular target for HCC therapy, providing new avenues for tumor treatment." (PMID 37373013, 2023). "Given that calponin 2 is expressed in various cell types including epithelial cells and inhibits cell proliferation and migration, we investigated calponin 2 expression in PDAC tumor tissues for potential roles in the development of PDAC." (PMID 28915602, 2017). "In the present study, we found that calponin 2 was not significantly expressed in normal pancreatic epithelial cells while its expression was increased in PDAC tumor cells." (PMID 28915602, 2017). "The χ2 test showed that CNN2 was expressed in all HCC patients regardless of tumor grade." (PMID 37373013, 2023).
cancer (9 papers, 2011 to 2024). A tumor composed of atypical neoplastic, often pleomorphic cells that invade other tissues. "Calponin 2 is present in smooth muscle, cardiac muscle, and multiple other cell types, including fibroblasts, endothelial cells, and cancer cells." (PMID 31569405, 2019). "Down regulation of calponin-2 (Q99439; CNN2) in Ghost pepper treated cells might be associated with morphological changes and detachment of cancer cells." (PMID 30379886, 2018). "Furthermore, we investigated the function of calponin 2 in cancer cell proliferation and metastasis using two PDAC cell lines." (PMID 28915602, 2017). "Besides, recently, accumulating evidence showed that CNN2 may take part in the development of malignant tumors because of its dysregulation and dysfunctions." (PMID 37188478, 2023).
CNN2 also shares sentences with these, for which no sentence is quoted: Hepatic fibrosis (2 papers); neurological disease (2); allergic asthma (1); allergic disease (1); asthma (1); cyst (1); diabetes (1); diabetes retinopathy (1); fibrosis (1); gestational diabetes (1); glioblastoma (1); liver cirrhosis (1); lung carcinoma (1); nasopharyngeal carcinoma (1); nephrogenic diabetes insipidus (1); neuroblastoma (1); Premature ovarian insufficiency (1); psychosis (1); rectal cancer (1).